CD74 (CD74 molecule)
Diseases named in the same sentence as CD74 in open-access papers (continued):
Sharing a sentence is not in itself a finding about the gene and the disease.
melanoma (continued). "Indeed, this mechanism seems plausible based on our previous observations that approximately 80% of patients with advanced melanoma were positive for CD74 in the tumor and tumor-infiltrating immune cells." (PMID 35121729, 2022). "In addition, The Cancer Genome Atlas (TCGA) and The Genotype-Tissue Expression (GTEx) RNA-sequencing data showed that CD74 mRNA expression in spleen and melanoma tissues was higher than that in normal tissues from other organs." (PMID 35121729, 2022). "The survival analysis in stage-III melanoma patients directed the question of whether sCD74 is a surrogate for the CD74-expressing tumor tissues or if sCD74, per se, features some biological activities regulating tumor behaviors." (PMID 35121729, 2022). "However, this has mostly been attributed to MHC class I. Zeiner and colleagues recently published a study showing that knockdown of CD74 in brain-seeking melanoma cells decreased the complexity of the MHC class II peptidome." (PMID 34944801, 2021). "Finally, Ekmekcioglu and colleagues found that CD74 expression in melanoma cells strongly correlates with improved OS and RFS in stage III melanoma patients." (PMID 33925387, 2021). "Our results showed that melanoma cells express CD74 associated with the progression from melanocytes and benign nevi to clinically evident melanoma but not any significant difference observed in earlier to late stages of disease." (PMID 33327409, 2020). "Therefore, we present our findings here that we have identified (and validated by TCGA dataset) the protein expression of CD74 as providing survival information for stage IV melanoma prognosis." (PMID 33327409, 2020). "Similarly, genes related to melanoma invasion were downregulated in SIRT2-deficient melanoma cell lines (e.g., HLA-DRA, IL-6, CD74, and HLA-DRB1 in the SSW30 clone, Dataset S1; PTPRZ1, FST, and NRCAM in the SSM15 clone, Dataset S2)." (PMID 31091806, 2019). "There is another important issue concerning the role of the CD74 in melanoma." (PMID 31013837, 2019). "Most interestingly, high CD74 expression on tumor cells was associated with prolonged patient overall survival after BM surgery in the total cohort as well as in our largest subcohorts of BM deriving from NSCLC and melanoma." (PMID 29490700, 2018). "We only found a weak significant positive correlation between PD-L1 and CD74 in BM from melanoma." (PMID 29490700, 2018). "Further immunohistochemistry revealed a weak positive staining for CD74, the HLA-DR associated invariant chain, negative staining for cytokeratins, the melanoma antigen HMB45 and CD34." (PMID 23880011, 2013). "In addition, MIF and CD74 have been identified as potential targets of anti-cancer therapeutics, including for cervical cancer, ovarian carcinoma, glioblastoma, multiple myeloma, and melanoma." (PMID 38730725, 2024). "The cytokine MIF (macrophage migration inhibitory factor) and its cognate receptor CD74 are intimately connected with cancer progression and have previously been proposed as prognostic biomarkers for patient outcome in various cancers, including solid tumors such as malignant melanoma." (PMID 38730725, 2024). "Furthermore, their study indicated that the signature CD74+/MIF− could be a more powerful prognostic marker in the case of stage III melanoma." (PMID 31013837, 2019). "MITF has been identified as a lineage survival oncogene amplified in malignant melanoma, CTLA-4 expression has been shown to be associated with a more favorable prognosis of patients with CM, and CD74 was identified as a useful prognostic marker associated with OS of patients in stage III melanoma." (PMID 31169496, 2019). "Pro-tumorigenic effects of IFN-γ may be, in part, due to pro-expression of CD74 in melanoma." (PMID 28060744, 2017). "Both recombinant and macrophage-derived sCD74 suppressed melanoma growth and triggered apoptosis by inhibiting the MIF/CD74/AKT survival pathway." (PMID 41597203, 2026).
melanoma (continued). "In one melanoma study, IFNγ-induced CD74 overexpression and MIF-CD74 signaling was shown to increase phosphorylated AKT levels, leading to elevated inflammatory cytokine production and promoting disease progression." (PMID 41597203, 2026). "We defined clusters corresponding to melanoma (PMEL, MLANA), immune infiltrates (TRBC2, TRAC, TMSB4X), melanophages (CD74, LYZ), keratinocytes (KRT14, TRIM29), blood vessels (CAVIN1, PECAM), and fibroblast‐enriched areas in the dermis (DCN, COL1A2, FBLN1)." (PMID 39846232, 2025). "In turn, the secretion of soluble CD74 (sCD74) was observed in melanoma cells and macrophages, while sCD74 suppressed melanoma cell growth and induced apoptosis, inhibiting the MIF/CD74/AKT pathway under IFN-γ stimulation." (PMID 40108693, 2025). "In the melanoma dataset, STModule identifies similar components from the two samples, including cancer cells (I), transition areas (II), lymphoid tissue (III; CD74, CD52, MS4A1), immune activities (IV-VI), CAFs, and melanocytes (GAPDH)." (PMID 40033360, 2025). "Upregulations of Cxcl9, Cxcl10, Cxcl11, Ccl5, Tap1, CD74, Irf1, Icam1, CD40, Fas and PD-L1 were detected after Mi-2β silencing and the anti-PD-1 treatment in BRafV600E/Ptennull melanomas." (PMID 38461299, 2024). "SpatialDB was used to determine the overlap between the distributions of CD74, the macrophage marker CD68, and the M1 macrophage marker CD86 in PRAD and melanoma tissues." (PMID 38582956, 2024). "Taken together, our data suggests measurement of CD74:MIF and CD74:DDT expression level ratios can provide prognostic information with respect to survival in patients with autoinflammatory disease and melanoma better than MIF, DDT, or CD74 alone." (PMID 39028303, 2024). "Previous studies have found that inhibiting MIF/CD74 signaling pathway can suppress AKT phosphorylation and promote tumor development in melanoma and esophageal squamous cell carcinoma." (PMID 38685050, 2024). "For verification, tissue sections were examined by fluorescence staining, showing co-expression of CD74 and CD86 in eight cancer types (BRCA, BLCA, esophageal squamous cell carcinoma, COAD, STAD, melanoma, cervical cancer, and osteosarcoma)." (PMID 38582956, 2024). "In melanoma and esophageal squamous carcinoma, blocking the MIF/CD74 signaling pathway inhibited AKT phosphorylation and promote tumor progression, whereas, in glioma, the MIF/CD74 axis inhibited IFN-γ secretion by promoting the phosphorylation of ERK1/2." (PMID 38685050, 2024). "In melanoma, MIF/CD74 cannot only regulate the expression of PD‐L1 but also affect the anti‐tumour immune response of macrophages and dendritic cells." (PMID 35060345, 2022). "Based on the FAM molecular subtypes, we identified the 6 FAMGs (ACSL5, ALOX5AP, CD1D, CD74, IL4I1, TBXAS1) that play vital regulatory roles in the melanoma TME." (PMID 36466837, 2022). "Both recombinant and THP-1 macrophage-released endogenous sCD74 suppressed melanoma cell growth and induced apoptosis under IFN-γ stimulatory conditions via inhibiting the MIF/CD74/AKT-survival pathway." (PMID 35121729, 2022). "Consistently, another recent study showed that IFN-γ enhances the expression of CD74, which interacts with its ligand and thereby activates the PI3K/AKT pathway in melanoma, leading to the promotion of tumor survival and growth." (PMID 35105915, 2022). "TGF-β-expressing B cells in the melanoma tumor microenvironment assembled in clusters and interacted with T cells via lymphoid recruitment (SELL, CXCL13, CCL4, CD74) signals and with Tregs via CD47:SIRP-γ, and FOXP3-promoting Galectin-9:CD44." (PMID 35909944, 2022). "IFN-γ has been reported to upregulate CD74, a class II MHC molecule that is highly expressed in melanoma tissues." (PMID 34222462, 2021). "Another study confirmed that CD74 is a useful tumour cell prognostic protein marker closely related to recurrence-free survival and overall survival in stage III melanoma." (PMID 34957096, 2021).
melanoma (continued). "In a xenograft melanoma model established by cell surface CD74-negative MeWo cells subcutaneously injected into the flank of SCID Beige mice, MIC-CD74 inhibition by MIC inhibitor ISO-1 suppresses tumor growth significantly." (PMID 28060744, 2017). "Beyond melanoma and HCC, CD74 has prognostic relevance in several other cancers." (PMID 41597203, 2026). "We found that TGFb can be secreted by immune cells (T_NK cells, B_Plasma cells, Myeloid cells), ECs, Fibroblasts, C2 PHLDA2+ Melanoma cells, C4 PCLAF+ Melanoma cells and C5 CD74+ Melanoma cells, and targeting C2 PHLDA2+ Melanoma cells and C4 PCLAF+ Melanoma cells." (PMID 39781353, 2025). "Associations between CD74 methylation and CTLs were also investigated using TIDE, with negative correlations seen in GBM, melanoma, TNBC, LIHC, and LUAD." (PMID 38582956, 2024). "Given the link between TIMP-1 and enhanced immunogenicity in melanoma, its interaction with CD74 might either bolster its MHC-I/II chaperoning role or compete with MIF, reducing MIF-induced suppressive effects through CD74." (PMID 38777826, 2024). "Thus, CD74:MIF and CD74:DDT expression ratio measurements offer promise as prognostic markers for survival outcomes and ICI response in patients with melanoma." (PMID 39028303, 2024). "We also observed higher sCD74 levels in patients whose melanoma tissues had high CD74 staining intensity compared with those whose melanoma had low CD74 expression, although the difference was not statistically significant (p = 0.077)." (PMID 35121729, 2022). "In the tumor microenvironment, the inhibition of the CD74-MIF signaling pathway could restore the antitumor activity of macrophage and dendritic cells against melanoma." (PMID 34540893, 2021). "Similar observation were determined in four CTC-positive melanoma-BM patients; most CTCs showed a strong expression of CD74 (15/26) and CD44 (19/26), with only one patient not showing any expression of either protein." (PMID 34209696, 2021). "The inhibition of CD74 and MIF could significantly attenuate the tumor growth of prostate cancer cells and melanoma mice model." (PMID 34540893, 2021). "In this current study, we have identified and validated the protein expression of CD74 (and together with MIF) as providing survival information, and propose that CD74+ and MIF− together be considered to form a “signature” for stage IV melanoma prognosis, as we found on stage III melanoma." (PMID 33327409, 2020). "It was reported that CD74 is expressed in melanoma but not in benign melanocytes using a melanoma progression tissue microarray." (PMID 28060744, 2017). "Furthermore, obstructing MIF/CD74-induced signalling in the TME emerges as a promising method to boost melanoma immunogenicity, irrespective of a vaccination strategy (GVAX)." (PMID 37454231, 2023). "Interestingly, we did not detect CD74 cell surface expression in unfixed H1 melanoma cells indicating a functional restriction to mainly intracellular compartments." (PMID 29490700, 2018). "We could not establish that the sensitivity of individual melanoma cell lines to MIF depletion resulted from the differential expression of known MIF receptors (i.e. CD74/CD44 and/or CXCR4)." (PMID 25168062, 2014). "Furthermore, high CD74 and MIF ratios correlated with increased pro-inflammatory markers and immune cell infiltration, suggesting that these ratios could serve as important indicators of immune response in melanoma." (PMID 41159021, 2025). "Moreover, in our initial efforts to understand CD74 role in melanoma progression, we performed similar analyses for CD74 on a melanoma progression TMA containing tissue cores from benign nevi, primary cutaneous melanomas, melanoma metastases to lymph nodes and visceral organs." (PMID 33327409, 2020).
breast carcinoma (45 papers, 2009 to 2026). "A few studies have also reported CD74 expression in breast cancer, especially associated to the triple negative subtype and breast cancers with lymph node metastasis." (PMID 37081824, 2023). "Although CD74 overexpression is mostly associated with hematologic malignancies, some studies have also reported CD74 expression in breast cancer especially associated to the triple negative subtype and metastatic breast cancer." (PMID 34944801, 2021). "Expression levels of proteins, encoded by CD74, were lower in the breast carcinoma samples than in normal tissue, suggesting expression differences at both the mRNA and the protein levels." (PMID 33854546, 2021). "A previous study suggested that CD74 was associated with poor prognosis and high tumor-infiltrating leucocyte in breast cancer, which was consistent with our finding." (PMID 34540893, 2021). "Using the online resource TIMER, we also found results that support that CD74 mRNA expression in breast cancer was associated with increased infiltration by immune cells." (PMID 34944801, 2021). "The three breast cancer cell lines exhibited yellow/orange fluorescence in single cell images, signifying closely associated CD74 and CD44 receptors (panel at the far right)." (PMID 29190904, 2017). "Chi-square analysis indicated that elevated expression of CD74 was associated with breast cancer; the CD74 expression level was increased in 143 of 189 (75.7%) cases with BIDC." (PMID 27626171, 2016). "High expression of CD74 has been reported to be associated with a variety of carcinomas, including breast cancer." (PMID 27626171, 2016). "Moreover, GSEA findings indicate that elevated CD74 expression is linked to the activation of a range of immune responses in breast cancer, including IFN-α and IFN-γ responses, and the IL6-JAK-STAT3 pathway." (PMID 38582956, 2024). "The present study establishes WISP1 as a nexus linking intracellular signaling to microenvironmental remodeling and identifies Lyn, MIF/CD74, and HA metabolism as promising therapeutic targets in breast cancer." (PMID 41597235, 2026). "While invasive breast cancers typically rely on high CD74 to maximize MIF-driven EMT, our results raise the possibility that ERα+ tumors such as MCF7 cells achieve similar outcomes through WISP1-mediated MIF amplification." (PMID 41597235, 2026). "Lastly, the combined inhibition of AEP and CD74 was proven to safely and effectively combat lung metastasis of breast cancer, providing novel insights for clinical treatment." (PMID 40411322, 2025). "High expression levels of Fib‐11 and CD74 were correlated with improved survival in breast cancer, whereas high SPP1 and CD44 expression predicted worse PDAC outcomes." (PMID 40357856, 2025). "Protein interaction analysis revealed a potential relationship between AEP and CD74 in influencing the EMT process of breast cancer cells." (PMID 40411322, 2025). "This suggests that the combined inhibition of AEP and CD74 can effectively overcome lung metastasis of breast cancer and improve the prognosis of mice." (PMID 40411322, 2025). "Our results indicate that Cd68+Cd74+ApoE+ macrophages play a crucial role in breast cancer metastasis to the lungs." (PMID 39695088, 2024). "In contrast, genes in the regulation of DNA damage signaling and cell cycle are downregulated upon high expression levels of CD74 in breast cancer." (PMID 39056676, 2024). "In MESO and breast cancer, high CD74 tumor cell expression at different cutoffs of histochemistry score (H-score) (MESO: H-score ≥ 400; breast cancer: H-score ≥ 20) was positively associated with longer survival." (PMID 38280003, 2024). "To this end, we analyzed transcriptomics gene expression profiles of breast cancer patients in the Gene Expression Omnibus database and found that CD74 is upregulated and correlated with aberrant elevation of various indicated cancer hallmarks." (PMID 39056676, 2024).
breast carcinoma (continued). "A study of human breast cancer showed that CD74 interacted with CD44 to promote tumorigenesis and metastasis of MDA-MB-231 cell through the regulation of RHOA." (PMID 38874510, 2024). "CD74 is highly expressed in basal-like breast cancer cell types and is significantly correlated with the number of tumor-infiltrating monocytes, indicating that CD74 is closely related to intratumoral immune regulation." (PMID 39118044, 2024). "We further validated and performed immunohistochemical staining of TNBC tissues derived from 6 patient derived xenograft (PDX) models using CD74 antibody and found that CD74 is highly expressed in an aggressive form of breast cancer, TNBC." (PMID 39056676, 2024). "We verified that CD74 interacts with TIMP‐1 in breast cancer cells and that this interaction contributes to cellular internalization of TIMP‐1 and mediates intracellular signaling through the Akt signaling axis in breast cancer cells." (PMID 37081824, 2023). "Several studies have demonstrated that CD74 is overexpressed in B‐cell neoplasms, and in solid tumors, including breast cancer." (PMID 37081824, 2023). "Of note, CD74 was observed to be related to triple-negative breast cancer, which is the most aggressive subtype of breast cancer." (PMID 36911401, 2023). "Briefly, we have identified multiple TIMP‐1 interactors and verified that CD74 is a novel TIMP‐1 cell surface binding protein in breast cancer cells." (PMID 37081824, 2023). "We discovered several potential interactors, and on closer inspection identified MHC class II‐associated invariant chain peptide (CD74), a protein known for its internalization properties, as a TIMP‐1 binding partner in breast cancer." (PMID 37081824, 2023). "To confirm that a physical interaction between TIMP‐1 and CD74 does take place in breast cancer cells, we performed co‐immunoprecipitation studies using MDA‐MB‐231 breast cancer cells cultured in the presence of rTIMP‐1." (PMID 37081824, 2023). "To determine the applicability of our findings to a broader context, we analyzed a breast cancer patient cohort for expression of CD74, CD63, and TIMP‐1 by immunohistochemistry (IHC)." (PMID 37081824, 2023). "In contradiction, CD74 or the invariant chain (Ii) expression was negatively correlated with HLA-DR expression in gastric cancer and breast carcinoma." (PMID 35208514, 2022). "For instance, increased infiltration of immune cells in breast cancer has been described after upregulation of CD74." (PMID 36142162, 2022). "CD44 and CD74 were expressed on most CTCs and their expression was strongly correlated, whereas matched breast cancer BM tissues were much less frequently expressing CD44 and CD74 (negative in 46% and 54%, respectively)." (PMID 34209696, 2021). "In breast cancer, CD74 has been described to be overexpressed in both cancer cells and cancer-associated stromal cells." (PMID 34944801, 2021). "Previous studies have found CD74 expression in human breast cancers to be correlated with generally adverse disease parameters such as increased presence of metastases and triple-negative status of the breast cancer." (PMID 34944801, 2021). "Previous studies examining CD74 expression in relation to clinical parameters in breast cancer have come to conflicting conclusions." (PMID 34944801, 2021). "Expression of CD74 was also significantly correlated with PD-L1 expression in the 1017 breast carcinomas available from the TIMER online analysis tool, even after correcting for tumor-infiltrating immune cells (p < 0.001)." (PMID 34944801, 2021). "Many of the studies addressing the effect of CD74 in breast cancer have relied on immunohistochemistry (IHC) with an anti-CD74 mouse monoclonal antibody (LN-2)." (PMID 34944801, 2021). "Correlation of high CD74 expression in 555 breast cancer samples from a TMA stained with UMAb231 samples and patient clinical data indicated that high expression of CD74 protein was positively associated with OS." (PMID 34944801, 2021).